RPL13AP17 (ribosomal protein L13a pseudogene 17 )
Synonyms: RPL13A_6_816
Gene: Long non-coding RNA gene on chromosome 7 (78,347,142 to 78,359,458, forward strand). Ensembl gene ENSG00000293158.
Diseases named in the same sentence as RPL13AP17 in open-access papers:
RPL13AP17 is named in the same sentence as 1 disease in open-access papers, as found by Europe PMC text mining. Sharing a sentence is not in itself a finding about the gene and the disease.
RPL13AP17 shares sentences with these, for which no sentence is quoted: tumor (1 paper).